BDNF (brain derived neurotrophic factor)
Diseases named in the same sentence as BDNF in open-access papers (continued):
Sharing a sentence is not in itself a finding about the gene and the disease.
Hyperglycemia (76 papers, 2011 to 2025). An increased concentration of glucose in the blood. "Our results revealed that hyperglycemia decreases BDNF and NeuN expression, causing cell damage and complications." (PMID 39139674, 2024). "Hyperglycemia and downregulation of both BDNF and TrkB in leptin deficient mice were recovered by adrenalectomy or low-dose corticosterone replacement, suggesting that glycemic status affects the BDNF/TrkB system through the HPA axis." (PMID 25309465, 2014). "Indeed, BDNF-mediated PI3K/Akt signaling prevents the downregulation of synaptic plasticity-associated proteins in hippocampal neurons induced via hyperglycemia." (PMID 35955546, 2022). "In addition, in an experimental study, changes in the BDNF signalling pathway were associated with insulin resistance and hyperglycaemia." (PMID 34234699, 2021). "Forward stepwise linear regression analysis underscored a similar trend with associations between hyperglycaemia, 24-hour BP [Adj R2 0.21–0.29; β 0.23 (0.1–0.4); p = 0.01], silent ischaemia [Adj R2 0.22; β 0.40 (0.2–0.6); p < 0.01] and cortisol:BDNF levels in Africans, mostly in the men." (PMID 27966001, 2016). "On the other hand, maternal hyperglycemia has been associated with reduced expression of brain-derived neurotrophic factor (BDNF), neuroinflammation, apoptosis in the hippocampus, and cellular damage in the dentate gyrus, all of which could contribute to neurodevelopmental deficits." (PMID 39518888, 2024). "Nevertheless, persistent hyperglycemia for 45 days significantly reduced BDNF levels in both the prefrontal cortex (P = 0.014) and the hippocampus (P = 0.030) compared to the sham group." (PMID 40726602, 2025). "Among these, skeletal muscle activity-induced BDNF secretion can enhance insulin secretion and reduce blood glucose levels during hyperglycemia]." (PMID 40933306, 2025). "The ability of BDNF to counteract hyperglycemia-induced damage via these pathways underscores its therapeutic potential in DR." (PMID 40003672, 2025). "Hyperglycemia affects nerve conduction and metabolism, resulting in decreased signaling and BDNF expression." (PMID 39139674, 2024). "Our results also revealed that hyperglycemia-induced neuroinflammation resulted in decreased NeuN and BDNF expression and abnormally increased GFAP expression in the HFD/STZ group." (PMID 38952685, 2024). "Our data are complementary to previously published results and show an inverse correlation between hyperglycemia and BDNF concentration." (PMID 35736415, 2022). "Taken together, the ability of β-OHB to attenuate hyperglycemia along with its potential to upregulate neuronal BDNF expression presents as a novel strategy for improving metabolic and brain health in people with increased cardiometabolic risk." (PMID 33013465, 2020). "Ingestion of a ketone monoester (KME) drink containing beta-hydroxybutyrate (β-OHB) attenuates hyperglycemia in humans and increases neuronal BDNF in rodents." (PMID 33013465, 2020). "Taken together, these data suggest that muscle can secrete BDNF into the circulation and plasma BDNF levels regulate insulin secretion in situations of hyperglycemia as observed in isolated islets." (PMID 32327658, 2020). "Hyperglycemia, AGEs, lipid peroxidation, and chemokines all increase the intracellular oxidant load, which can decrease the BDNF blood level in situ." (PMID 32405353, 2020). "Mechanistically, hyperglycemia downregulates BDNF release from the brain in lean, normoglycemic men." (PMID 33013465, 2020). "Our results support a model in which skeletal muscle activity induces BDNF secretion, enhancing insulin secretion and glucose removal from the blood during hyperglycemia." (PMID 32327658, 2020). "We found that hyperglycemia significantly increased the expression of NF-κB p65 and p-NF-κB p65 in the hippocampus (p<0.05), while BDNF significantly decreased the expressions (p<0.05) compared with that in the EGFP+STZ group." (PMID 31165005, 2019).
Hyperglycemia (continued). "More interestingly, BDNF inhibited hyperglycemia-induced microglial activation and reduced elevated levels of inflammatory factors (TNF-α, IL-6)." (PMID 31165005, 2019). "BDNF also restores the morphology of activated microglia induced by hyperglycemia close to the resting state and suppresses the increased levels of TNF-α and IL-6." (PMID 31165005, 2019). "Acute hyperglycemia downregulates circulating plasma BDNF via reduced output from the brain in healthy adults, and adults with T2D appear to have lower resting BDNF levels, possibly due to chronic hyperglycemia." (PMID 30363954, 2018). "Africans had increased incidence of hyperglycaemia and 24-hour silent ischaemic events, and elevated 24-hour blood pressure (BP) and cortisol:BDNF ratios compared to Caucasians." (PMID 27966001, 2016). "BDNF has been shown to inhibit apoptosis in rat retinal ganglion cells at early stages of DR and it has been shown that BDNF protects retinal neurons from hyperglycemia through the Tropomyosin-related kinase B (TrkB)/ERK/MAPK pathway." (PMID 27313539, 2016). "Both central and peripheral administration of BDNF decrease food intake, increase energy expenditure, and ameliorate hyperglycemia in diabetic mice by a central nervous-system-mediated mechanism." (PMID 21837282, 2011). "In addition, long-term exercise can improve insulin sensitivity and vascular endothelial function, reducing the inhibition of BDNF expression by hyperglycemia." (PMID 40933306, 2025). "When brain BDNF levels are depleted, it can lead to excessive nutrition and increased body weight, which are often accompanied by metabolic syndrome characterized by hyperleptinemia, hyperglycemia, and hyperinsulinemia." (PMID 39199870, 2024). "Hyperglycemia may downregulate BDNF expression in proximal tubular cells and enhance fibrosis in renal tissue." (PMID 39355615, 2024). "Potential corresponding targets in hyperglycemia-injured renal tissue comprise brain-derived neurotrophic factor (BDNF), which has been proven to contribute to kidney deterioration through autophagy attenuation, fibrosis progression, oxidative stress imbalance, and microinflammation." (PMID 37547923, 2023). "In rodents, changes in the BDNF signalling pathway lead to hyperglycaemia." (PMID 34234699, 2021). "However, when expressed as incremental AUC, hyperglycemia appears to reduce circulating BDNF in lean men only." (PMID 33013465, 2020). "Speculatively, the protection of BDNF during OGTT in NW may be due to the glucose attenuation, given that acute hyperglycemia downregulates BDNF release from the brain." (PMID 33013465, 2020). "Conversely, acute hyperglycemia reduces cerebral output of BDNF in young adults, which may be a mechanism to explain lower plasma BDNF in adults with T2D." (PMID 33013465, 2020). "Thus a reduction of BDNF can thus serve to reduce glucose control, which can have a feedback effect by inhibiting the cerebral output of BDNF as shown in pathway: 7-26-BDNF-44-72-14-55-hyperglycaemia." (PMID 26231223, 2015). "Young age, female sex, hyperglycemia (including fasting glucose and HbA1c), high total cholesterol, hypertriglyceridemia, normal UACR, use of statins and metformin, and no use of α-glucosidase inhibitor were significantly associated with high serum BDNF levels." (PMID 39355615, 2024). "Dysfunction in the brain may result from disturbances in neuronal glucose transport and metabolism, increased free radical production, or decreased brain-derived neurotrophic factor (BDNF) production during hyperglycemia, as the brain is primarily dependent on glucose." (PMID 38952685, 2024). "Additionally, the cerebral output of BDNF is inhibited under hyperglycemia, logically decreased serum BDNF may be detected in the uncontrolled T2DM patients." (PMID 38648255, 2024).
Hyperglycemia (continued). "The observed hyperglycemia-induced RGC loss and reduced retinal thickness replicated previous preclinical and clinical studies where RGC loss was one of the earliest morphological signs of DR associated with reduced expression of brain-derived neurotrophic factor (BDNF)." (PMID 33498409, 2021). "Raising β-OHB via KME may be a strategy for increasing/protecting BDNF during hyperglycemia." (PMID 33013465, 2020). "Strategies that can attenuate hyperglycemia may positively impact circulating BDNF." (PMID 33013465, 2020). "Some of the studies confirmed the existence of a correlation between hyperglycemia and DPP4 activity, BDNF and cognitive impairment." (PMID 35468904, 2022). "MFE attenuated hyperglycemia-induced memory impairments and acetylcholine deprivation, protected neuronal cells in CA1 and CA3 regions via p-CREB/BDNF pathway activation, and reduced amyloid-β precursor protein and p-Tau expressions in the brain tissue." (PMID 32454931, 2020). "Based on the results, Gas inhibited hyperglycemia-induced ERS and NLRP3 inflammasome activation and increased BDNF expression in the hippocampal neurons." (PMID 30524286, 2018). "Our observation of decreased BDNF in AIS/DM patients aligns with prior clinical studies reporting reduced BDNF in diabetic populations, potentially due to platelet BDNF depletion from hyperglycemia-induced platelet hyperactivity." (PMID 41280373, 2025). "Secondly, the specific patient characteristics, such as poorer glycemic control (mean HbA1c of 8.31% in our cohort), more severe hyperglycemia, or the co-occurrence of AIS, might counteract the potential BDNF-elevating effects of metformin." (PMID 41280373, 2025). "For the first time, it was highlighted: (a) the role of TIR in the activation of the pAkt/CREB/BDNF pathway and the downstream signaling cascade; (b) TIR efficacy in neuroprotection; (c) TIR counteracting of hyperglycemia and insulin resistance-related effects at the neuronal level." (PMID 38287296, 2024). "Hesperidin reduced hyperglycaemia, decreased malondialdehyde (MDA) and IL-6 levels, and enhanced the brain-derived neurotrophic factor (BDNF) and monoamines in the brain, thereby enabling it to be effective in treating and managing neurogenesis in diabetic rats." (PMID 32977511, 2020). "In summary, hyperlipidemia and hyperglycemia in DM rats could decrease hippocampal GLUT3 protein level and increase ERS, leading to decreased BDNF expression by disturbing the ER function and positively suppressing the NLRP3 pathway." (PMID 30524286, 2018). "Furthermore, the effects observed on CREB and BDNF promoter methylation and in regulating miR-34a, miR-212, and miRNA-29c levels, highlighted the role of TIR in overcoming the epigenetic modifications induced by hyperglycemia." (PMID 38287296, 2024). "Therefore, we examined changes in AKT, GSK3β, NeuN, BDNF, and GFAP expression in a rat model, and our data showed that AKT and downstream GSK3β expression was reduced in the brains of rats with HFD/STZ-induced hyperglycemia." (PMID 38952685, 2024). "Although, studies show that BDNF level may decrease in T2DM in response to hyperglycemia, we did not observe such a correlation in our research." (PMID 33918576, 2021). "The reduction in circulating BDNF with hyperglycemia is likely due to changes in cellular release of BDNF as opposed to changes in platelet dynamics, as Araki and colleagues found that plasma, but not serum, BDNF decreases following an OGTT in children with normal and impaired glycemia." (PMID 33013465, 2020). "Our study showed that hyperglycemia results in enhanced expression of HMGB1 mRNA and protein, while BDNF overexpression inhibits the increased expression of HMGB1 in the hippocampus of diabetic mice, suggesting a possible role of HMGB1 in mediating the anti-inflammatory effects of BDNF." (PMID 31165005, 2019).
Hyperglycemia (continued). "In particular, the ability of BDNF to improve insulin sensitivity and influence energy expenditure suggests that it could help mitigate the effects of postprandial hyperglycemia and contribute to the lack of ketosis during fasting periods in bottlenose dolphins." (PMID 39199870, 2024). "However, whether BDNF is sufficient to prevent or reverse the hyperglycemia-induced brain damages has not been directly investigated." (PMID 31165005, 2019). "However, whether BDNF can alleviate neuroinflammation induced by hyperglycemia has not been investigated until now." (PMID 31165005, 2019).
Rett syndrome (75 papers, 2011 to 2026). A severe neurodevelopmental disorder affecting the central nervous system. "Other Rett syndrome studies utilised Brain Derived Neurotrophic Factor (BDNF), a molecule associated with neuroprotection." (PMID 39948021, 2025). "In a trial of the drug Fingolimod in children with Rett syndrome, CSF BDNF levels were higher at baseline and were associated with better clinical scores." (PMID 39948021, 2025). "For instance, previous studies have demonstrated a reduction in the hippocampal expression of the nerve growth factor associated with a tendency to increased hippocampal BDNF levels in another mouse model of developmental disorder, the Rett syndrome." (PMID 37566006, 2023). "A novel treatment targeting MAPK-related pathways has been described to improve motor function in a mouse model of Rett syndrome, and a BDNF increase in the motor-related cortex has been associated with improvements in motor coordination in the mouse." (PMID 34413771, 2021). "In Rett syndrome, the presence of the Val/Met BDNF polymorphism has been associated with slightly greater clinical severity consistent with the current study where girls with the Val/Met polymorphism had the poorest gross motor skills at baseline." (PMID 29321033, 2018). "BDNF dysfunction has been implicated in pathophysiological mechanisms of Rett syndrome, the most common intellectual disability in women after Down syndrome (1:10,000 incidence)." (PMID 28751857, 2017). "In human Rett syndrome patients, a Val/Met polymorphism in BDNF has been associated with disease severity." (PMID 24238429, 2013). "Moreover, in a mouse model of Rett’s syndrome, early therapy with fingolimod attenuates motor symptoms in association with enhanced BDNF-mediated striatal neuroprotection." (PMID 41516369, 2026). "It is also shown that the variation, c.Val66Met located in the BDNF gene has been associated with increased BDNF serum concentration in depressed patients and c.Val66Met has identified as a possible genetic modifier of disease severity in Rett syndrome." (PMID 33503967, 2021). "Environmental enrichment could benefit children in the early stages of Rett syndrome and increased BDNF levels could be associated with improvements." (PMID 29321033, 2018).